AFP (alpha fetoprotein)
Diseases named in the same sentence as AFP in open-access papers (continued):
Sharing a sentence is not in itself a finding about the gene and the disease.
gastric cancer (continued). "The GC with a high level of AFP is termed α-fetoprotein-producing gastric cancer (AFPGC)." (PMID 24083471, 2013). "Some studies have demonstrated that the other tumors in human could also produce AFP and gastric cancer was one of the most common." (PMID 23382965, 2013). "The serum level of AFP also increased in AFP-producing gastric cancer." (PMID 22540862, 2012). "AFP-secreting gastric cancers occur with a frequency of 2% to 6%." (PMID 22018031, 2011). "Moreover, AFP-producing gastric cancer is reported to respond poorly to a number of chemotherapy regimens." (PMID 17634124, 2007). "Few successful treatment options exist for AFP-producing gastric cancer." (PMID 17634124, 2007). "Alpha-fetoprotein-producing gastric cancer (AFP-GC) is a rare but aggressive subtype of gastric cancer (GC), marked by increased serum alpha-fetoprotein (AFP) levels and AFP positivity on immunohistochemical (IHC) analysis." (PMID 40082418, 2025). "Consequently, AFP is regarded as a significant biomarker in gastric cancer research." (PMID 40485723, 2025). "The authors concluded that AFP-positive gastric cancer might benefit more from this regimen." (PMID 38355790, 2024). "Since AFP could influence immunity by both inhibiting natural killer (NK) cells and regulating negatively the function of dendritic cells, we evaluated the influence of baseline serum alpha-fetoprotein (AFP) levels on the curative effect of ICIs in advanced gastric cancer (AGC) patients." (PMID 38408930, 2024). "Alpha-fetoprotein-producing gastric cancer (AFPGC) is a rare type of aggressive gastric cancer (GC) with a dismal prognosis." (PMID 37150760, 2023). "AFP-positive gastric cancer (AFPP-GC) is a rare entity, the incidence of which is reported to be 1-15% among GC patients." (PMID 37781207, 2023). "Therefore, it is recommended that physicians routinely examine the level of serum AFP in gastric cancer patients, especially in patients with liver metastasis, while pathological specimens of routine AFP immunohistochemistry can greatly improve the detection rate of GC." (PMID 35886934, 2022). "This study aimed to compare the genetic landscape of HAS with liver hepatocellular carcinoma (LIHC), gastric cancer (GC), and AFP-producing GC (AFPGC) and identify clinically actionable alterations." (PMID 36010842, 2022). "This suggested that AFP may be related to the distant metastasis of gastric cancer." (PMID 35611170, 2022). "Other tumors, such as gastric cancer (GC), colorectal cancer, lung cancer, and ovarian cancer, can also lead to elevated AFP." (PMID 35847953, 2022). "The aim of this work is to study the clinicopathological features and prognostic factors of serum alpha-fetoprotein (AFP)–positive gastric cancer (GC)." (PMID 35847953, 2022). "In this present study, thirty-five cases of AFP-producing gastric cancer were retrospectively summarized and intriguingly a couple of characteristics of AFP-producing GC were identified." (PMID 29254216, 2017). "In addition, some reports showed that AFP could also be produced by other tumors, including gastric cancer, rectal cancer, pancreas cancer, gallbladder cancer, lung cancer, and bladder cancer." (PMID 29434637, 2017). "Although decreased risk of gastric cancer was found in blood type O positive among common GC patients by a meta-analysis, our present study firstly unveil that blood type O (15 cases, 42.8%) positive were predominantly observed among AFP-GC patients." (PMID 29254216, 2017). "We consider this rare case to have significant value with respect to treatment of AFP-producing gastric cancer with multiple liver metastases, and propose that combining surgery with chemotherapeutic agents such as paclitaxel may lead to a better prognosis in such cases." (PMID 17634124, 2007). "Alpha‐fetoprotein‐producing early gastric cancer (AFPGC) is typically diagnosed at an advanced stage with high malignant potential and accounts for 1.2%–6.6% of all gastric cancers." (PMID 41190289, 2026).
gastric cancer (continued). "The AUCs for serum CA125, AFP, CEA, and their combined detection in predicting clinical outcomes of gastric cancer patients were 0.713, 0.809, 0.922, and 0.926, respectively (P<0.001)." (PMID 40406247, 2025). "The ROC curves of serum CA125, AFP, CEA, and their combined detection for the TNM staging of gastric cancer were respectively plotted, and the AUCs were 0.751, 0.834, 0.911, and 0.931, respectively (P<0.001)." (PMID 40406247, 2025). "Further analysis through ROC curve plotting revealed that the AUCs for serum CA125, AFP, CEA, and their combined detection in diagnosing metastasis of gastric cancer were 0.716, 0.825, 0.863, and 0.892, respectively (P<0.001)." (PMID 40406247, 2025). "This study presents a novel contribution by systematically evaluating, for the first time, the clinical utility of the combined detection of CA125, AFP, and CEA in the diagnosis and prognostic assessment of gastric cancer." (PMID 40406247, 2025). "While previous studies by the authors have examined various aspects of tumor marker interactions in gastric cancer, the specific relationship between TNF-α and the combined serological panel of AFP, CEA, CA19-9, and CA72-4 remains unexplored." (PMID 40299527, 2025). "The positive rates of serum CA125, AFP, and CEA in the gastric cancer group were also significantly higher compared to the benign group (6.98% vs. 1.51%, 4.16% vs. 1.01%, 19.86% vs. 5.98%), with statistically significant difference (P<0.05)." (PMID 40406247, 2025). "This study utilized the clinically prevalent tumor markers CA125, AFP, and CEA as research indicators to analyze their respective application value in gastric cancer patients with various pathological features and prognoses." (PMID 40406247, 2025). "The AUCs for CA125, AFP, CEA, and their combined detection in diagnosing gastric cancer were 0.815, 0.813, 0.911, and 0.919, respectively (P<0.001)." (PMID 40406247, 2025). "The AUCs for serum CA125, AFP, CEA, and their combined detection in TNM staging of gastric cancer were 0.751, 0.834, 0.911, and 0.931, respectively (P<0.001)." (PMID 40406247, 2025). "The present study aimed to investigate the correlations between plasma TNF-α levels and established tumor markers (AFP, CEA, CA72-4, and CA19-9) in gastric cancer patients, with particular attention to how these relationships vary across disease stages." (PMID 40299527, 2025). "Serum levels of CA125, AFP, and CEA were significantly higher in the gastric cancer group compared to the benign group, with statistically significant difference (P<0.05)." (PMID 40406247, 2025). "In our case, treatment included standard gastric cancer protocols (which proved most effective), GCT protocols (considering AFP production), and investigational agents." (PMID 40922714, 2025). "Serum levels of CA125, AFP, CEA, and their positive rates were significantly higher in the gastric cancer group compared to the benign group (P<0.05)." (PMID 40406247, 2025). "Serum levels of CA125, AFP, and CEA in patients with gastric cancer were significantly elevated and were correlated with the degree of differentiation and TNM staging." (PMID 40406247, 2025). "The results suggested that the serum levels of CA125, AFP, and CEA were significantly higher in patients with gastric cancer than in those with benign lesions." (PMID 40406247, 2025). "Building upon our previous study focused on AFP's cellular machinery in HCC cells and DEN-induced liver tumors in mice, we expanded our investigation into the role of AFP in gastric cancer." (PMID 39135041, 2024). "Last decades have witnessed a growing interest in alpha-fetoprotein (AFP)—producing gastric cancer (AFPGC), also known as AFP-positive or AFP-elevated gastric cancer, due to its aggressive phenotype and poor prognosis." (PMID 38833154, 2024). "Therefore, gastric cancer with both elevated levels of AFP and CEA may have a worse prognosis." (PMID 39902132, 2024).
gastric cancer (continued). "Certain serum markers, such as AFP and CEA, are utilized for gastric cancer screening and monitoring, yet their specificity is suboptimal and susceptible to external factors, resulting in an elevated misdiagnosis rate." (PMID 38515458, 2024). "Serum biomarkers such as CEA, CA19-9, AFP, CA72-4, and CA12-5 have limited ability as a detection marker for early gastric cancer." (PMID 39409942, 2024). "In conclusion, this study provides insights into the role of AFP in promoting HCC and gastric cancer proliferation through c-Myc and c-Met regulation." (PMID 39135041, 2024). "Other tumor markers reported in gastric cancer are CA72‐4, alpha‐fetoprotein, (AFP), CA125, and sialyl Tn antigen (STN)." (PMID 38455491, 2024). "Based on the TCGA-STAD data, we plotted the ROC curves of AFP and CEA for the diagnosis of gastric cancer." (PMID 38515458, 2024). "This study explored the crucial role of AFP in HCC and gastric carcinoma, uncovering its involvement in cancer proliferation through the regulation of c-Myc and c-Met." (PMID 39135041, 2024). "AFP-GC and HER2 overexpressed gastric cancer were categorized into the CIN subtype, which was the largest category, comprising approximately 50% of gastric cancers." (PMID 37354221, 2023). "Serum tumor markers such as AFP, Carcinoembryonic antigen (CEA), CA19–9, CA72–4 and CA24–2 already used to assess the biological behavior and progression of gastric cancer." (PMID 36647059, 2023). "AFP-GC has been categorized as a unique subtype of gastric cancer (GC)." (PMID 37588998, 2023). "This study aimed to investigate whether α-fetoprotein (AFP) could affect the malignant behavior of AFP-producing gastric cancer (AFP-GC) and to explore the relationship between AFP and mesenchymal–epithelial transition factor (c-Met) in AFP-GC." (PMID 37588998, 2023). "Both AFP-GC and HER2 overexpressed gastric cancer has been known for aggressive clinical behavior and poor prognosis." (PMID 37354221, 2023). "Another study revealed that the AUCs of AFP, CEA, CA125, and CA199 in detecting gastric cancer were 0.519, 0.583, 0.553, and 0.585, respectively." (PMID 35879835, 2023). "Although AFP, as a star marker, has currently been utilized in clinical settings for the detection of various cancers, including HCC, gastric cancer, and breast cancer, to date, there is no SPR aptasensor for AFP." (PMID 37143897, 2023). "Alpha-fetoprotein (AFP)-producing gastric cancer (AFPGC) is a relatively rare disease, accounting for 1.3–15% of gastric cancer patients." (PMID 36076263, 2022). "Immunohistochemistry showed serum hepatoid marker alpha-fetoprotein (AFP) and GPC3 positivity in gastric cancer tissues from patients with elevated AFP and GPC3." (PMID 35050429, 2022). "In the M1 stage, the sensitivity of AFP, CEA, CA125, CA199, and CA242 to detect gastric cancer was 34.33%, 49.25%, 62.69%, 52.24%, 52.24%, respectively, and the sensitivity of combined detection was 71.64%." (PMID 35611170, 2022). "In the early stages of gastric cancer, tumor markers such as carcinoembryonic antigen (CEA), alpha-fetoprotein (AFP), cancer antigen (CA) 19-9, CA 125, and CA 24-2 have been used for diagnosis and prognosis of the disease." (PMID 35547460, 2022). "Carcinoembryonic antigen (CEA), carbohydrate antigen 199 (CA199), carbohydrate antigen 724 (CA724), alpha-fetoprotein (AFP), and carbohydrate antigen 125 are currently accessible tumor markers for the screening or early identification of gastric cancer." (PMID 36703788, 2022). "Although some biomarkers, such as CEA, CA199, AFP, CA125, Her-2 and serum Helicobacter pylori antibodies 26, 27, have been reported as the prognostic value in gastric cancer patients, more progress in early diagnosis and treatment is urgently needed." (PMID 35399734, 2022). "In the M0 stage, the sensitivity of AFP, CEA, CA125, CA199, and CA242 to detect gastric cancer was 9.95%, 16.92%, 5.47%, 14.43%, 14.93%, respectively, and the sensitivity of combined detection was 35.82%." (PMID 35611170, 2022).
gastric cancer (continued). "For example, the incidence of AFP-producing gastric cancer (GC) is approximately 1.3–15% in GC." (PMID 34680245, 2021). "The most commonly used tumor markers of gastric cancer were CEA, CA19-9, CA72.4, and CA125, sometimes plus AFP and CA242." (PMID 34246249, 2021). "Preoperative testing and postoperative dynamic observation of serum AFP levels are beneficial for the early diagnosis of HAS and the evaluation of treatment efficacy, and their inclusion in routine screening for gastric cancer should be considered." (PMID 34956891, 2021). "To date, the biomarkers commonly used in early screening for gastric cancer include carcinoembryonic antigen (CEA), alpha-fetoprotein (AFP), carbohydrate antigen 19–9 (CA19–9), CA72–4, CA125, etc.." (PMID 32460771, 2020). "Accordingly, studies on the surgical treatment of liver metastasis from gastric cancer may have unexpectedly included many AFP-GC patients." (PMID 32093729, 2020). "Immunohistochemically, the adenocarcinomatous component with clear cytoplasm comprised areas with alpha-fetoprotein (AFP)- and Sal-like protein 4 (SALL4)-positive AFP-producing gastric carcinoma." (PMID 32972454, 2020). "We found that AFP, LIN28B, and SALL4 were overexpressed in seven, eight, and nine cases of the 200 human gastric cancers, respectively." (PMID 29802314, 2018). "Levels of CEA, CA19-9, AFP, and CA125 are also widely used to monitor recurrence or metastasis of gastric cancer after radical gastrectomy." (PMID 27533455, 2016). "Although gastric cancer patients with normal, preoperative serum CEA, CA19-9, AFP, and CA125 had favorable prognoses, the prognostic value of relatively high levels of the four tumor markers within the normal limits was important to test." (PMID 27533455, 2016). "It has been widely reported that higher rates of serum CEA, AFP and CA19-9-positivity in gastric cancer are correlated with larger tumors, higher T status, and upper third tumor." (PMID 27418046, 2016). "The prognostic value of the combination of CA19-9, AFP, and CA125 for gastric cancer was also evaluated." (PMID 27533455, 2016). "Further, the combination of relatively high levels of CA19-9, AFP, and CA125 increased the prognostic value for gastric cancer, even though the levels were all within the normal limits." (PMID 27533455, 2016). "A large number of studies have investigated the predictive value of elevated preoperative serum CEA, CA19-9, AFP, and CA125 levels for the prognosis of gastric cancer." (PMID 27533455, 2016). "A 63-year-old man was found to have a huge Type 3 gastric cancer with a PVTT and a highly elevated serum AFP level." (PMID 25591731, 2015). "The average serum level and the positive rate of AFP, CEA, CA125 and CA19-9 in gastric cancer group were higher than that in the benign gastric disease group and the healthy control group." (PMID 23672279, 2013). "The sensitivity of AFP, CEA, CA125 and CA19-9 in the diagnosis of gastric cancer was 4.7-20.8% individually, and increased to 40.3% in combination." (PMID 23672279, 2013). "In this study we analyzed the diagnostic value of four common clinical serum tumor markers AFP, CEA, CA125 and CA19-9 for gastric cancer." (PMID 23672279, 2013). "However, serum AFP levels sometimes are elevated in patients with primary gastric cancer (GC) as well." (PMID 24083471, 2013). "In this study we detected the serum levels of tumor markers AFP, CEA, CAl25 and CAl9-9 in 149 patients with gastric cancer, 111 patients with benign gastric diseases and 124 healthy people." (PMID 23672279, 2013). "Some serum tumor markers including alpha-fetoprotein (AFP), carcinoembryonic antigen (CEA), carbohydrate antigen (CA) 19-9, CA50, and CA72-4 have been reported to be elevated in some patients with gastric cancer." (PMID 22540862, 2012). "The aim of this study was to evaluate the prognostic value of AFP, CEA, CA19-9, and CA50 in T4a stage gastric cancer." (PMID 22540862, 2012).
gastric cancer (continued). "We found that the serum levels of AFP, CEA, CA19-9, and CA50 were significantly correlated with survival rate in patients with T4a stage gastric cancer, which was in agreement with previous studies of AFP, CEA, and CA19-9." (PMID 22540862, 2012). "Among these tumors, AFP, CEA, CA19-9, CA50, and CA72-4 were considered as relatively specific markers for gastric cancers." (PMID 22540862, 2012). "Primary gastric cancer could show elevated serum AFP of gastric production of primitive foregut origin, such as the liver, and AFP produced hepatic metastatic lesions; reported incidence of AFP producing gastric cancer has been from 1.3-15% of all cases of gastric cancer." (PMID 21592404, 2011). "In our study, AFP-positive gastric cancer patients demonstrated significantly lower survival rates at 1, 3, and 5 years compared to AFP-negative patients." (PMID 40485723, 2025). "The results of this study indicated that the serum levels of CA125, AFP, and CEA in gastric cancer patients were significantly elevated, suggesting that these markers may have diagnostic efficacy for gastric cancer." (PMID 40406247, 2025). "Although AFP is not commonly used as a biomarker for gastric cancer, elevated levels have been observed in some cases, particularly in the advanced stages." (PMID 40430002, 2025). "Lastly, rapid tumor proliferation, with highly expressed progression marker Ki67 with low apoptotic index and high microvessel density (neovascularization), was noticed in the AFPGA compared to the AFP-negative gastric cancers (P<0.01)." (PMID 38817451, 2024). "The study also showed that even in the AFP-negative cases, 30% of patients with gastric cancer with metachronous liver metastasis had the GAPEP phenotype." (PMID 38355790, 2024). "We also detected that even in the AFP-negative cases, 30% of patients with gastric cancer with metachronous liver metastasis had the GAPEP phenotype." (PMID 38355790, 2024). "The expression in primary gastric cancer with metachronous liver metastasis, regardless of perioperative serum AFP levels, was analyzed." (PMID 38355790, 2024). "Furthermore, our results indicate that inhibiting AFP or HSP90 enhances the cytotoxicity of chemotherapeutic agents in AFP-producing HCC and gastric cancer cells." (PMID 39135041, 2024). "AFPGC has high proliferative activity, weak apoptotic activity, and rich neovascularization compared with AFP-negative gastric cancer." (PMID 36076263, 2022). "The positive levels of AFP and CA125 are related to the distant metastasis of gastric cancer." (PMID 35611170, 2022). "Biomarkers of tumor, such as AFP, β-subunit of human chorionic gonadotropin (β-hCG), CA125, and cytokeratin subunit 19 fragment (Cyfra21.1) have been widely used for the diagnosis of gastric cancer." (PMID 35886934, 2022). "The positive levels of AFP and CA125 were related to the distant metastasis of gastric cancer." (PMID 35611170, 2022). "Tumor markers contributing significantly to gastric cancer screening included CA199, CA125, AFP, and CA242 were identified, which might be considered as important inspection items for gastric cancer screening." (PMID 36526664, 2022). "A consensus regarding the treatment of recurrent alpha-fetoprotein-producing gastric carcinoma due to its rarity is lacking." (PMID 36051651, 2022). "Significant differences were observed between gastric cancer patients with and without HBsAg positive in terms of sex, age, family history of cancers, and AFP level (p < 0.05)." (PMID 33934530, 2021). "Fetal gut-like morphology is not uncommonly seen in AFP-producing carcinoma of the stomach and the lung: carcinomas with this pattern are called enteroblastic carcinoma in the stomach and fetal adenocarcinoma in the lung." (PMID 34977100, 2021). "The prognostic value of AFP is already reported in several types of cancers (e.g., gastric cancer and ovarian cancer), but there is no study available that explored its diagnostic and prognostic value in lung cancer." (PMID 32582542, 2020).